FTMT (ferritin mitochondrial)
Diseases named in the same sentence as FTMT in open-access papers (continued):
Sharing a sentence is not in itself a finding about the gene and the disease.
myelodysplastic syndrome (2 papers, 2014 to 2021). A clonal hematopoietic disorder characterized by dysplasia and ineffective hematopoiesis in one or more of the hematopoietic cell lines. "Subjects carrying mutations in the GATA2 gene have a high risk of developing the myelodysplastic syndrome and this pathogenic event may be responsible for the expression of FtMt in mutated cells." (PMID 34440737, 2021). "Moreover, a study on the DNA variations of human FtMt in patients affected by myelodysplastic syndromes and by movement disorders identified some variations, but no disabling mutations." (PMID 24728422, 2014). "Under physiological conditions, FtMt is not found in erythroid cells, but it was shown that, under pathological conditions (like the myelodysplastic syndrome refractory anemia with ring sideroblasts, MDS-RARS), it is highly expressed in sideroblasts." (PMID 34440737, 2021).
myocardial infarction (2 papers, 2025). Gross necrosis of the myocardium, as a result of interruption of the blood supply to the area, as in coronary thrombosis. "Previous studies reported that FTMT deficiency enhanced ferroptosis and exacerbated ventricular tachyarrhythmias after myocardial infarction in mice." (PMID 41415578, 2025). "In vivo experiments showed that overexpression of FTMT improved cardiac function in rats, as evidenced by the reduction of MI/RI‐induced serum CK‐MB, LDH and Fe2+ content and the shrinkage of myocardial infarction area." (PMID 40551312, 2025).
Stroke (2 papers, 2021 to 2022). Sudden impairment of blood flow to a part of the brain due to occlusion or rupture of an artery to the brain. "It remains to be clarified whether the lack of FtMt is the primary cause of a disorder and whether the modulation of its expression, which is useful as an inhibitor of neoplastic growth in stroke and in neurodegenerative disease, can also be considered a valid therapeutic approach in humans." (PMID 34440737, 2021).
virus infection (2 papers, 2024 to 2025). "In addition to confirming FTH as an established target of NCOA4, we now provide evidence that NCOA4 also regulates FTMT during virus infection." (PMID 40197059, 2025). "Besides confirming FTH as an established NCOA4 target, we now provide evidence that FtMt is also under the control of NCOA4 during virus infection." (PMID 38226812, 2024).
brain injury (1 paper, 2024). Acute and chronic (see also brain INJURIES, CHRONIC) injuries to the brain, including the cerebral hemispheres, CEREBELLUM, and brain STEM. "On the other hand, FtMt regulates the availability of free iron in the body, thereby preventing iron aggregation, oxidative stress, and ferroptosis in conditions such as brain I/R injury and indicating that FtMt could be considered a potential target for preventing ferroptosis-induced brain injury." (PMID 37548939, 2024).
breast carcinoma (1 paper, 2024). "Notably, our results show that DMT1 silencing induces PINK1/Parkin-dependent mitophagy as well as FTMT in MDA-MB-231 but not in T47D breast cancer cells." (PMID 38184712, 2024).
cognitive decline (1 paper, 2019). "This is supported by studies demonstrating that overexpression of mitochondrial ferritin (FtMt) attenuates Aβ-induced neuronal apoptosis, while Aβ-induced cognitive decline and neuronal apoptosis were exacerbated in FtMt KO mice relative to WT mice." (PMID 31057691, 2019).
diabetic cardiomyopathy (1 paper, 2025). Diabetic cardiomyopathy is a disorder of the heart muscle in people with diabetes. "In conclusion, GA pretreatment attenuated diabetic cardiomyopathy by downregulating TSPO expression, which subsequently promoted FTMT upregulation." (PMID 41415578, 2025). "GA was shown to attenuate diabetic cardiomyopathy by inhibiting ferroptosis and protecting mitochondria via the TSPO/FTMT signaling pathway." (PMID 41415578, 2025).
dopaminergic neuroblastoma (1 paper, 2024). A neuroblastoma associated with increased dopamine excretion. "In dopaminergic neuroblastoma, light has been shed on the overexpression of mitochondrial ferritin (FtMt), which was found to inhibit the cellular labile iron pool (LIP), which further causes the accumulation of ROS, protecting from ferroptosis effects." (PMID 38540208, 2024).
epilepsy (1 paper, 2024). A brain disorder characterized by episodes of abnormally increased neuronal discharge resulting in transient episodes of sensory or motor neurological dysfunction, or psychic dysfunction. "However, the potential role of FtMt in epilepsy remains unclear." (PMID 38439636, 2024).
neuronal tumor (1 paper, 2015). Neuronal brain tumors are an uncommon group of central nervous system tumors that arise from cells with neuronal differentiation. "Therefore, we further investigated the underlying mechanisms of FtMt’s inhibitory effects on neuronal tumor cell proliferation." (PMID 25213357, 2015). "We conclude that FtMt may be explored as a new target for inhibiting the proliferation of neuronal tumors." (PMID 25213357, 2015).
Obesity (1 paper, 2023). Accumulation of substantial excess body fat. "In another scenario, mimicking obesity-associated impairment of mitochondria in the adipose tissue through mitochondrial ferritin (FtMT) overexpression in mice also prompts adipocytes to release smaller EVs such as exosomes." (PMID 37805581, 2023).
preeclampsia (1 paper, 2023). Preeclampsia is a hypertensive disorder of pregnancy that is characterized by new-onset hypertension with proteinuria presenting after 20 weeks of gestation, and depending on mild or severe forms may initially present with severe headache, visual disturbances, and hyperreflexia. "This allowed us to investigate the effect of FtMt on cell function after hypoxia treatment, thus reflecting its role in the pathogenesis of preeclampsia." (PMID 36859279, 2023).
progressive supranuclear palsy (1 paper, 2023). A rare late-onset neurodegenerative disease characterized by supranuclear gaze palsy, postural instability, progressive rigidity, and mild dementia. "In our previous study, we implemented a 3D analysis to trace the spatial localization of FtMt and LC3 immunofluorescence signals and further ascertain their colocalization in nigral neurons of patients with progressive supranuclear palsy." (PMID 36672153, 2023).
neurodegenerative disease (11 papers, 2014 to 2026). A disorder of the central nervous system characterized by gradual and progressive loss of neural tissue and neurologic function. "We also summarize recent advances in understanding the association between FtMt dysregulation and various diseases, emphasizing its implications in neurodegenerative diseases, cardiovascular disorders and cerebrovascular pathologies." (PMID 41844496, 2026). "Mitochondrial ferritin (FtMt) is a mitochondrial iron storage protein associated with neurodegenerative diseases." (PMID 35008961, 2022). "A number of studies have demonstrated that increased levels of FtMt in cells have significant protective effect from a range of insults linked to production of ROS, including those associated with neurodegenerative disease mechanisms." (PMID 30670947, 2018). "Dysregulation of FtMt expression was associated with neurodegenerative diseases." (PMID 35008961, 2022). "Interestingly, FtMt has been recently been implicated as a neuroprotective factor in neurodegenerative disease through regulation of iron homeostasis in the brain." (PMID 25140149, 2014). "Mitochondrial ferritin (FtMt) is identified as an iron-storage protein located in the mitochondria, and its role in regulation of iron hemeostasis in neurodegenerative diseases has been reported." (PMID 28840060, 2017). "Previous studies have indicated that FtMt plays an important role in protecting cells from iron-dependent oxidative damage, particularly in neurodegenerative diseases." (PMID 28840060, 2017). "These recent findings on FtMt regarding its functions in regulation of brain iron homeostasis and its protective role in pathogenesis of neurodegenerative diseases are summarized and reviewed." (PMID 24596558, 2014). "Current findings suggested important roles of FtMt in the pathogenesis of neurodegenerative diseases." (PMID 24596558, 2014). "This study would be useful for understanding the roles of FtMt in neurodegenerative diseases." (PMID 28840060, 2017). "Interestingly, mitochondrial ferritin (FTMT), as a novel iron-storage protein in mitochondria, participates in regulating iron distribution between cytosol and mitochondrial contents and has a protective effect in pathogenesis of neurodegenerative diseases in cell models." (PMID 34299144, 2021).
tumor (7 papers, 2015 to 2024). "Knowing the role of FtMt in triggering a cellular iron deficient phenotype, it was proposed that its expression could inhibit tumor growth by removing iron from neoplastic cells." (PMID 34440737, 2021). "In addition, it was demonstrated that FtMt affected the cell cycle, causing G1/S arrest, and upregulated the expression of tumor suppressors, proving it can inhibit neuronal tumor cell proliferation." (PMID 34440737, 2021). "FtMt overexpression disturbed the iron homeostasis of neuronal tumor cell and significantly downregulated the expression of proliferating cell nuclear antigen." (PMID 29348829, 2017). "The proliferation and apoptosis assay demonstrated that inhibition of PKA was able to abrogate the tumor-killing effects of Roflumilast via down-regulating the expression of FtMt in OVCAR3 and SKOV3 cells." (PMID 29348829, 2017). "Our recent studies showed that FtMt overexpression protected 6-hydroxydopamine-indeced dopaminergic cell damage, and FtMt played inhibitory effects on neuronal tumor cell proliferation." (PMID 28066232, 2016). "This fourfold increase in signal from FtMt-overexpressing cells indicates that FtMt overexpression strongly inhibits tumor cell division." (PMID 25213357, 2015). "As expected, FtMt overexpression disturbed the iron homeostasis of tumor cells and significantly downregulated the expression of proliferating cell nuclear antigen." (PMID 25213357, 2015). "Our previous studies and those of others have shown that FtMt is also involved in the regulation of oxidative stress, but little is known about its exact function, especially in tumor tissue." (PMID 25213357, 2015). "To evaluate if the growth-inhibitory effects of elevated FtMt on tumor may be through these regulator proteins, we tested the expression of these proteins or genes by Western blot analysis and qRT-PCR, respectively." (PMID 25213357, 2015). "We thus propose FtMt as a new candidate target for inhibiting neuronal tumor cell proliferation." (PMID 25213357, 2015). "We therefore hypothesized that increased expression of FtMt may negatively affect the vitality of neuronal tumor cells." (PMID 25213357, 2015). "Similarly, when we knockdown the CREB levels in two cell lines, the expression of FtMt was remarkably decreased, which could restore the anti-tumor effects of Roflumilast, including cell vitality, apoptosis and cell cycle." (PMID 29348829, 2017). "Appropriate regulation of FtMt expression may prevent tumor cell growth." (PMID 25213357, 2015). "Interestingly, iron chelation specifically increases the expression of FTMT and the translocation of its precursor to the OMM, inducing mitophagy and suppressing tumor development." (PMID 38184712, 2024). "So far, the exact function of FtMt is not clear, in normal or tumor cells." (PMID 25213357, 2015).
cancer (5 papers, 2007 to 2024). A tumor composed of atypical neoplastic, often pleomorphic cells that invade other tissues. "The negative correlation between TfR1 and FtMt may suggest that FtMt plays an important role in iron metabolism and cancer cell proliferation." (PMID 25213357, 2015). "As in the cancer cell lines, we observed promoter hypomethylation in the primary tumors; the frequency of hypomethylation was 5% (1/20) for ANKRD30A, 20% (4/20) for FLJ40201, 0% (0/20) for INSL6, 30% (6/20) for SOHLH2, 20% (4/20) for FTMT, 25% (5/20) for C12orf12, and 30% (6/20) for DPPA5." (PMID 17967063, 2007).
neurological disorders (3 papers, 2014 to 2025). "Further studies regarding the detailed mechanisms of the regulation of FtMt expression and the role FtMt plays in neurological disorders associated with abnormal iron metabolism are important topics that need to be explored in the future." (PMID 24596558, 2014). "To investigate the possibility to modulate the FTMT epigenetic control in pathological models, we chose FRDA, a neurological disorder caused by the deficiency of frataxin (FXN), a mitochondrial iron-chaperon involved in iron sulfur cluster biosynthesis." (PMID 27625068, 2016). "The increased expression of FtMt in AD, PD, and other neurological disorders may relate to its neuroprotective role against iron overload and oxidative stress." (PMID 24596558, 2014).
infection (2 papers, 2025). The state of being infected such as from the introduction of a foreign agent such as serum, vaccine, antigenic substance or organism. "Western blotting analysis revealed that PPRV infection suppressed the expression of GPX4 and FTMT in mitochondrial fractions at 24 and 48 h and in a dose-dependent manner at 48 h." (PMID 40197059, 2025). "Ferritin heavy chain 1 (FTH1), ferritin light chain (FTL), mitochondrial ferritin (FTMT), and ATP6V1F were the downregulated genes identified in A. baumannii without resistant gene infection-associated pulmonary host response." (PMID 39857726, 2025).
FTMT also shares sentences with these, for which no sentence is quoted: restless legs syndrome (3 papers); cardiac failure (2); atherosclerosis (1); cardiovascular disorder (1); diabetes (1); movement disorder (1); Parkinson’s (1); Senile plaques (1).